CD47 (CD47 molecule)
Diseases named in the same sentence as CD47 in open-access papers (continued):
Sharing a sentence is not in itself a finding about the gene and the disease.
tumor (continued). "CD47 is expressed at increased level on the cell surface by a variety of malignant cells; its blockade with monoclonal antibodies allows the efficient phagocytosis of cancer cells and leads to tumor rejection and development of antitumor immunity." (PMID 33956406, 2021). "CD47 promotes cancer development by enabling tumor cells to escape phagocytosis." (PMID 34943817, 2021). "Moreover, HT can promote the proportion of M1 macrophages and enhance the anti-tumor effect of anti-CD47 antibody." (PMID 34858184, 2021). "Thus, overexpression of CD47 enables tumor cells to evade immune surveillance via the blockade of phagocytic mechanisms." (PMID 34717705, 2021). "Although TAMs maintain the ability to phagocytose tumor cells to some extent, tumor cells often express high levels of CD47 molecules that bind to signal regulatory protein α (SIRPα) on the surface of TAMs, sending the “don’t eat me” signal and inhibiting the phagocytic activity of TAMs." (PMID 35070992, 2021). "In addition, CD47/SIRPα interaction also has roles in tumor cell apoptosis, proliferation and migration." (PMID 34944850, 2021). "In addition to regulating angiogenesis and perfusion of the tumor vasculature, thrombospondin-1 limits antitumor immunity by CD47-dependent regulation of innate and adaptive immune cells." (PMID 33925464, 2021). "In addition, hypoxia upregulates the Macrophage Immune Checkpoint CD47 (commonly known as the “Don’t Eat Me” signal) inducing tumor cell escape from phagocytosis." (PMID 33807260, 2021). "Furthermore, in pre-clinical xenograft immunodeficient mouse models, anti-CD47 mAbs are used at high doses to induce tumor suppression, potentially over-estimating the likely efficacy of CD47 blockade in humans even in combination with direct targeting mAbs." (PMID 34638388, 2021). "CD47, a transmembrane protein, is widely overexpressed on the tumor cell surface." (PMID 33917794, 2021). "Notably, a recent study showed that SLAMF7 expression on target cells and binding to SLAMF7 on phagocytes mediated by coupling to Mac-1 are critical for the elimination of tumor cells by phagocytosis in CD47-blocking therapy." (PMID 33597728, 2021). "Blockade of CD47 signaling reactivates phagocytosis and promotes tumor eradication." (PMID 34966389, 2021). "The RS17 peptide interacted with human CD47 on two human tumor cell lines." (PMID 33629544, 2021). "Antibodies against the “do not eat me” signal CD47 cause macrophage phagocytosis of live tumor cells and drive the emergence of antitumor T cells." (PMID 33956406, 2021). "CD47 is an important tumor antigen for the development and progression of various cancers." (PMID 34189144, 2021). "Interestingly, there was no functional data showing the role of SIRP in B cells, while SIRPα was reported to be a critical regulator of myeloid cell activation via binding to CD47 and SIRPα/CD47 axis limited the efficacy of tumor-opsonising antibodies." (PMID 35003068, 2021). "Another study found that antibody blockade of CD47 significantly increased phagocytosis of hepatocellular carcinoma cells by macrophages and promoted infiltration of proinflammatory macrophages into tumor tissue to further eliminate tumor cells." (PMID 34178692, 2021). "In tumour immunotherapy, CD47 ligation by anti-CD47 antibodies or TSP1 induces G1-phase cell cycle arrest in Epstein-Barr virus (EBV)-transformed B cells through ROS generation, suggesting an appealing therapeutic intervention in EBV-associated tumours." (PMID 33920030, 2021). "However, tumor cells have evolved to engage the immune checkpoints, e.g., CD47 and PD-L1, and down-modulate the immune cells, thereby evading the antitumor immune response." (PMID 34625564, 2021). "The anti-CD47 mAbs therapy may also face challenges in the combination therapies, including tumor cell-specific antibodies and T-cell checkpoint inhibitors." (PMID 34717705, 2021).
tumor (continued). "By recruiting additional immune cells to tumours and synergizing the response of innate and adaptive immunity, CD47 blockade has displayed tremendous pharmacological advantages for preventing tumour recurrence and treating advanced‐stage malignancies and complications." (PMID 33449453, 2021). "Furthermore, phagocytosis of tumor cells by APCs was enhanced by blocking the anti-phagocytosis molecule CD47 in combination with TMZ, inducing an effective anti-tumor immune response." (PMID 34485282, 2021). "Anti-CD47 therapy enhances phagocytosis of tumor cells by macrophages." (PMID 33937269, 2021). "Therefore, the authors sought to direct the ADCP-enhancing activity of targeting CD47 to GPC3+ tumor cells using a bispecific approach." (PMID 34069573, 2021). "We should realize that future improvements in cancer screening and precision medicine will enable the identification and stratification of specific tumor types and/or stages of cancer that would be most amenable to treatment with a certain type or types of anti-CD47 treatment." (PMID 34305918, 2021). "Expression of CD47 in the tumor microenvironment is regulated by oncogenes, including MYC." (PMID 33925464, 2021). "CD47 is regularly expressed on all the normal cells and overexpressed on tumor cells." (PMID 34367975, 2021). "Thus, CD47 provides a potent “don’t eat me” signal that allows tumor cells to evade immune destruction by first-responder phagocytic cells and functions as a dominant macrophage checkpoint." (PMID 33799989, 2021). "Therefore, combining TAM modulation with CD47-blockade immunotherapy holds great promise for effective prevention of postsurgical tumor recurrence and metastases in clinic." (PMID 34138357, 2021). "Moreover, inhibition of CD47 in tumor cells promoted their phagocytosis and the anti-tumor activity of CD8 T cells while inhibiting T-reg cells." (PMID 34447383, 2021). "In addition to targeting tumor antigens, it is also of interest to target multiple immune checkpoints, such as CD47 and PD-L1." (PMID 33790906, 2021). "Considering that tumor-associated macrophages are one of the major players of GBM mediated immunosuppression, clincal trials combining vaccination with an anti-CD47 adjuvant could prove to be quite efficacious." (PMID 34041034, 2021). "CD47 is a highly glycated, anti-phagocytic molecule expressed on macrophages that is also widely distributed on the surfaces of various cells, such as tumor cells, red blood cells, and cardiomyocytes." (PMID 34349643, 2021). "Another therapeutic target, which is probably more relevant for pediatric brain tumors with elevated myeloid cell infiltration, is cluster of differentiation 47 (CD47) on tumor cells that binds to signal-regulatory protein alpha (SIRPα) on myeloid cells and inhibits macrophage-induced phagocytosis." (PMID 34830753, 2021). "Upon macrophage or dendritic cell-mediated phagocytosis of cancer cells by CD47 blockade, these phagocytes may present tumor antigens to T cells to induce anti-tumor T cell responses." (PMID 34305918, 2021). "Therefore, CD47 on CD8+ T cells functions as an adaptive immune checkpoint that mediates TSP1-dependent inhibition of tumor cell killing." (PMID 33925464, 2021). "Neoantigens and nucleic acid remnants, produced from dying cancer cells and released into the tumor microenvironment after chemotherapy, may potentiate anti-CD47 activity." (PMID 34944850, 2021). "JMT601 (CPO107) blocked the expression of CD47 on tumor cells and SIRPα on macrophages." (PMID 34717705, 2021). "In recent years, more and more studies have shown that CD47 could be one of the key immune checkpoint molecules in tumor therapy." (PMID 34776955, 2021). "Besides, another crucial role of the TSP-1:CD47 signaling axis emerged that leads to tolerogenic signals allowing tumor immune escape through direct inhibition of T-cell activation." (PMID 34638503, 2021).
tumor (continued). "In addition, based on the ability of HT to promote M1 macrophages, we further evaluated the anti-tumor effect of HT in combination with anti-CD47 antibody." (PMID 34858184, 2021). "In the present study, our specific focus has been to investigate whether the CD47/SIRPα axis is involved in the VES-induced anti-tumour effect." (PMID 34093795, 2021). "A relatively lower expression of CD47 in tumor cells or higher CD163+ TAMs was related to poor prognosis, suggesting that they might act as indicators for PanNET prognosis." (PMID 33765961, 2021). "CD47 is an innate immune checkpoint highly expressed on the surface of tumor cells." (PMID 33815422, 2021). "However another central role of the TSP-1:CD47 signaling axis emerged that leads to tolerogenic signals and allows tumor immune escape through direct inhibition of T-cell activation, as well as by regulating natural killers and dendritic cells functions." (PMID 34638503, 2021). "Free heme as well as RRx-001 mediated downregulation of CD47 expression on tumor cells and SIRPα expression on macrophages induces a shift from the low phagocytic M1 phenotype to the high phagocytic M2 phenotype in tumor cells." (PMID 33946824, 2021). "These MPs directly phagocytize tumor cells expressing low levels of the “don’t eat me” signal CD47, release pro-inflammatory factors that activate Th1 and Th17 immune responses and can also produce TNF-related apoptosis-inducing ligand (TRAIL) that result in TRAIL-induced cancer cell apoptosis." (PMID 33418996, 2021). "Moreover, effector T cells can be activated for enhanced antitumor efficacy upon phagocytosis of tumor cells through CD47 blockade." (PMID 34138357, 2021). "A cluster of differentiation 47 (CD47) is widely overexpressed in various malignancies and might be a predictor of poor prognosis and tumor metastasis." (PMID 35071016, 2021). "CD47, known as the “don't-eat-me” signal, is commonly overexpressed on the surface of tumor cells." (PMID 33763066, 2021). "RS17 can inhibit tumor immune escape by blocking the CD47‐SIRPα signaling pathway." (PMID 33629544, 2021). "However, a variety of tumor cells have upregulated CD47 protein on their surface, which can interact with signal regulatory protein alpha (SIRPα) on M1-like TAMs and trigger evasion of tumor cells from macrophage recognition." (PMID 34138357, 2021). "The results indicated that HT can enhance the anti-tumor effect of anti-CD47 antibody." (PMID 34858184, 2021). "Indeed, Bifidobacterium has been found to facilitate local anti-CD47 immunotherapy on tumor tissues through the capacity to accumulate within the tumor microenvironment, via the signaling pathway of STING." (PMID 34604233, 2021). "Several molecules, such as CD47 (“do not eat me” signal), which are implicated in tumor immune escape mechanisms and can be targeted by small-molecule drugs, have now become targets of gene-editing approaches utilizing NPs as a delivery system for CRISPR/Cas9." (PMID 34683963, 2021). "Studies have shown that CD47 plays a key role in immune regulation and tumor development." (PMID 34610581, 2021). "In total, 35% of the CRCs (95/269) exhibited CD47 expression on the cytomembrane of tumor cells." (PMID 33799989, 2021). "For this reason, increased prophagocytic calreticulin expression through CD47-targeted NIR-PIT could provide additional tumor cytotoxicity." (PMID 34064074, 2021). "Therefore, the inhibition of the CD47-Sirpα signaling axis promotes macrophage phagocytic ability against tumor cells." (PMID 34576180, 2021). "Blockade of CD47 reduced tumor burden both in vitro and in vivo." (PMID 34966389, 2021). "Overexpression of CD47 could protect tumor cells from phagocytosis and is a promising therapeutic target in cancer therapy." (PMID 34610581, 2021). "We also showed that FF alone or in combination with a CD47 antibody (MIAP410) could increase the ability of macrophages to inhibit tumor proliferation in vivo and in vitro." (PMID 33937269, 2021).
tumor (continued). "One of the main events that can be detected in the early stages of ICD is the translocation of calreticulin from the cytoplasm to the tumor cell membrane, which provides macrophage stimulation via the “eat me” signal that is antagonized by CD47 expressed on the tumor cell membrane." (PMID 34639014, 2021). "CD47 expression displayed a significantly increased expression in PanNETs, providing more evidence for the concept that the increase of CD47 expression in tumor would aid escape immunosurveillance of the host." (PMID 33765961, 2021). "Regarding the fibroblast subsets defined as CD56+, those coexpressing CD47 were predominantly found in tumor samples from patients 2 and 3, while the cell subset defined singly by CD56 expression was mainly found in the mechanically dissociated tissues from all three patients." (PMID 33670410, 2021). "A blockade of CD47/SIRPα could reactivate the phagocytosis of macrophages and enhance the anti-tumor immunity." (PMID 34068552, 2021). "Interestingly, with MF progression, the LGALS9-CD47 interaction switches places: in plaque MF, exhausted BTLA+ CD4+ T cells express CD47, and the tumor cells express ligand LGALS9, but in tumor MF, the opposite occurs." (PMID 34885092, 2021). "Thus, anti-CD47-secreting anti-PD-L1 CAR-T cells improved the anti-tumor activity and achieved a significant survival benefit from an epitope-spreading mechanism." (PMID 33567640, 2021). "The authors found that CD47 inhibition also promoted tumor phagocytosis by microglia, and in vivo live imaging showed that CD47 inhibition reduced the number of microglial processes, increased process straightness, and reduced the speed of process extension and retraction." (PMID 33763064, 2021). "Besides, murine models suggest that adaptive immunity contributes to tumor control upon targeting the SIRPα-CD47 pathway." (PMID 33936033, 2021). "Increased probability of tumor node metastasis is associated with the enhanced serum levels of cathepsin S (CTSS) that possess a substantial role during the invasiveness of HCC and CD47 promotes CTSS expression via NF‐κB activation." (PMID 32902664, 2021). "Therefore, inhibiting CD47-SIRPα signal transduction promotes the phagocytosis of tumor cells by macrophages and inhibits tumor growth." (PMID 34683963, 2021). "Previous findings have demonstrated that conventional therapies, such as chemotherapy‐mediated upregulation of cell surface calreticulin and radiotherapy‐induced inflammation, increased the sensitivity of the tumour to macrophages, all of which contributed to the outcomes of anti‐CD47 treatment." (PMID 33449453, 2021). "Actually, it was shown that suppressing SIRPα-CD47 signaling, which is a don’t eat me signal, and promoting tumor phagocytosis by TAMs could be a therapeutic approach for various tumors." (PMID 34685535, 2021). "We found that HT enhanced the anti-tumor effect of anti-CD47 antibody." (PMID 34858184, 2021). "In addition, tumors can send a “don’t eat me” signal to macrophages through immune checkpoint CD47-SIRPα to prevent tumor cells from phagocytosis." (PMID 34858184, 2021). "CD47 is overexpressed in almost all tumor cells and closely related to clinical prognosis." (PMID 34805154, 2021). "Potential limitations of targeting the CD47/SIRPα axis includes the ability to target agents into the tumor and toxicity such as cytopenias, which may potentially be overcome by novel therapeutic strategies." (PMID 34944850, 2021). "In the acidic TME, cleavage of the benzoimine bond of the nanobioconjugate released anti-SIRPα and anti-CD47, which blocked SIRPα on the macrophages and CD47 on the tumor cells, thereby eliminating the “don’t eat me” signal and improving macrophage phagocytosis ability." (PMID 34885247, 2021). "CD47 / SIRP-α signaling pathway is an important way for tumor immune escape." (PMID 33391402, 2021).
tumor (continued). "In vivo studies on 4T1 tumor-bearing mouse model demonstrated that the DLG-based strategy efficiently prevented tumor recurrence and metastasis by locally reversing the immunosuppression and synergistically blocking the CD47-dependent immune escape, thereby boosting the systemic immune responses." (PMID 34138357, 2021). "FF combined with anti-CD47 significantly inhibited tumor cell proliferation in tumor-bearing mice." (PMID 33937269, 2021). "Furthermore, SIRPα specific monoclonal antibody KWAR23 disrupts SIRPα-CD47 interaction resulting in inhibition of tumor growth by increasing phagocytosis." (PMID 34512146, 2021). "Anti-SIRPα antibodies can enhance phagocytosis when combined with tumor-opsonizing anti-CD47 mAbs." (PMID 34717705, 2021). "Recent research found that Bifidobacterium can enhance local anti-CD47 immunotherapy in tumor." (PMID 34267748, 2021). "In fact, above induction of the pro-survival and proliferation gene, MYC controls the expression of different immune checkpoint proteins on the tumor cell surface, such as the innate immune regulator, CD47 (cluster of differentiation 47), and NK-activating ligands, such as MICA/B and PVR." (PMID 34503175, 2021). "The combination of the anti-CD47 antibody and anthracyclines has shown good therapeutic efficacy for orthotopic breast cancer; this antibody eliminates M2 macrophages and Tregs in the tumor microenvironment." (PMID 34638242, 2021). "Consistent with previous reports describing tumor-derived EVs, immune checkpoints CD47 and CD274/PD-L1, and key regulators of myeloid differentiation (e.g., TRIB1, SOCS3, STAT3) were upregulated in EwS EV-treated cells compared to control, with TC32 EVs generally eliciting stronger effect." (PMID 34440851, 2021). "In addition, a cancer xenograft mouse model was established using CD47‐expressing HepG2 cells to evaluate the effect of RS17 on tumor growth in vivo." (PMID 33629544, 2021). "Inhibition of tumor angiogenesis could be the rationale of the potential therapeutic effect of CD47 as an anti-cancer therapy." (PMID 32677994, 2020). "After discovering the CD47-SIRPα recognition mechanism of tumor cells and macrophages, researchers used an anti-CD47 monoclonal antibody to carry out in vivo experiments on tumor-bearing mice, and found the antibody can block the CD47-SIRPα pathway to interdict the signal of anti-phagocytosis." (PMID 32161718, 2020). "Given that the binding of CD47 with SIRPα in tumor cells limits the anti-cancer immune response, it is possible that therapies that inhibit CD47 signaling in cancer cells would promote the phagocytosis of tumor cells by macrophages and thereby limit tumor growth." (PMID 32082311, 2020). "The detection of high affinity SIRPα binding on tumor cells may prove to be a better indicator of response to therapy than measures of CD47 mRNA or protein expression." (PMID 32240171, 2020). "CD47 overexpression may contribute to the immune escape of tumor cells through the inhibition of ADCP, via the binding of CD47 to the signal-regulatory protein alpha (SIRPα) on TAMs." (PMID 31936617, 2020). "In addition, blocking the myeloid checkpoint of Signal regulatory protein alpha (SIRPα)/CD47 has shown to be efficient improving tumor phagocytosis and thus decreasing tumor burden." (PMID 33585220, 2020). "We found RQ may decrease the expression levels of CD47 and SIRPα on tumor cells and macrophages, respectively." (PMID 32020472, 2020). "The association between CD47 and HER2 may also explain the acquired resistance in BC patients treated with anti-HER2 modality and the limited tumor inhibition with RT combined with CD47 blockade." (PMID 32929084, 2020). "Disrupting the CD47–SIRPα interaction bridges innate and adaptive antitumor immune mechanisms; therefore, we determined the activity of hAB21 in multiple syngeneic murine tumor models as a monotherapy or in combination with immune checkpoint inhibitors." (PMID 33256806, 2020).